MX1 (MX dynamin like GTPase 1)
Description:
Interferon-induced dynamin-like GTPase with antiviral activity against a wide range of RNA viruses and some DNA viruses. Its target viruses include negative-stranded RNA viruses and HBV through binding and inactivation of their ribonucleocapsid. May also antagonize reoviridae and asfarviridae replication. Inhibits thogoto virus (THOV) replication by preventing the nuclear import of viral nucleocapsids. Inhibits La Crosse virus (LACV) replication by sequestering viral nucleoprotein in perinuclear complexes, preventing genome amplification, budding, and egress. Inhibits influenza A virus (IAV) replication by decreasing or delaying NP synthesis and by blocking endocytic traffic of incoming virus particles. Enhances ER stress-mediated cell death after influenza virus infection. May regulate the calcium channel activity of TRPCs.
Synonyms: IFI-78K; MxA; lncMX1-215; IFI78; MX
Tractability: Small molecule: a structure with a bound ligand is known; it has a binding pocket of medium quality. Antibody: UniProt places it where antibodies can reach, with high confidence; its Gene Ontology location is reachable by antibodies, with medium confidence. PROTAC: UniProt records ubiquitination sites on it; ubiquitination databases record sites on it; its protein half-life has been measured.
Gene: Protein-coding gene on chromosome 21 (41,420,020 to 41,470,071, forward strand). Ensembl gene ENSG00000157601.
Subcellular location: Cytoplasm; Endoplasmic reticulum membrane; Cytoplasm, perinuclear region; Cytoplasm (Isoform 2); Nucleus
Subcellular location (Human Protein Atlas): Cytosol; Nuclear membrane
Pathways (Reactome):
Immune System: ISG15 antiviral mechanism; Interferon alpha/beta signaling
Gene Ontology:
Molecular function: identical protein binding; protein binding; GTP binding; microtubule binding; GTPase activity
Biological process: antiviral innate immune response; defense response to virus; interleukin-27-mediated signaling pathway; negative regulation of viral genome replication; response to virus; apoptotic process; defense response; innate immune response; response to type I interferon; signal transduction; synaptic vesicle budding from presynaptic endocytic zone membrane
Cellular component: cytoplasm; cytosol; endoplasmic reticulum membrane; nuclear membrane; nucleus; perinuclear region of cytoplasm; plasma membrane; synapse; nuclear envelope; presynapse
Genetic constraint (gnomAD): Loss-of-function variants: 63 observed, 66.43 expected, observed/expected ratio (o/e) 0.95, 90% interval 0.77 to 1.17. The upper end of that interval is the gene's LOEUF score, 1.17, which puts it in group 5 of 6, group 1 being the genes least tolerant of losing a copy. Missense variants: 754 observed, 841.09 expected, observed/expected ratio (o/e) 0.9, 90% interval 0.84 to 0.95. Synonymous variants: 302 observed, 321.87 expected, observed/expected ratio (o/e) 0.94, 90% interval 0.85 to 1.03.
Homologues: Orthologues: macaque MX1 (95% identical), pig MX1 (78% identical), rat Mx2 (70% identical), rat Mx1 (65% identical), mouse Mx2 (54% identical), tropical clawed frog mx1 (52% identical), mouse Mx1 (41% identical). Paralogues in human: MX2 (60% identical), DNM2 (30% identical), DNM3 (30% identical), DNM1 (29% identical), DNM1L (28% identical), OPA1 (22% identical).
Diseases named in the same sentence as MX1 in open-access papers:
MX1 is named in the same sentence as 245 diseases in open-access papers, as found by Europe PMC text mining. Sharing a sentence is not in itself a finding about the gene and the disease. The quoted sentences say what the papers report.
viral infection (279 papers, 2006 to 2026). "MX1 is anticipated to impact the severity of viral infection and the extent of harm it causes to different cell types that participate in lymphocyte activation." (PMID 41012169, 2025). "First, SARS-CoV-2 infection was associated with upregulation of MX1, a protective factor whose expression was reported to be switched-on in several viral infections including SARS-CoV-2." (PMID 38116398, 2023). "IRF9 deficiency has been reported to increase susceptibility to several forms of viral infections and result in decreased levels of MX-1 and ISG-1541." (PMID 36273032, 2022). "While MX Dynamin Like GTPase 1 (MX1) is an interferon-inducible protein that is associated with viral infections by influenza and viral encephalitis." (PMID 33301474, 2020). "Associating gene expression with suppression of viral infection is a reasonable strategy to identify ISGs with obvious antiviral performance, exemplified by the influenza inhibitor, MX dynamin like GTPase 1 (MX1), and the human immunodeficiency virus 1 inhibitor, MX dynamin-like GTPase 2 (MX2)." (PMID 36399061, 2022). "Furthermore, there seem to be several genes that are common between SARS-CoV-2 infection and other respiratory-causing viral infections such as MX1 which was also differentialy expressed in rotavirus infectoins." (PMID 35003208, 2021). "Finally, while anti-viral specificity of MX1 is largely determined by a disordered loop (L4) in the stalk domain, antiviral specificity of MX2 is determined by the N-terminal domain (NTD), indicating that the mechanisms underlying inhibition of viral infection by MX1 and MX2 are distinct." (PMID 38512975, 2024). "Previous studies have reported that MX1 polymorphisms could influence the antiviral and enzymatic activities, which can be expected to insight into the molecular mechanisms of inter-individual variabilities in susceptibility and severity of viral diseases." (PMID 38429664, 2024). "For Mx1, virus infection induced a robust and persistent increase in mRNA levels compared to control cells (P < 0.01)." (PMID 40406095, 2025). "Interferon-stimulated genes (ISGs) and IFN-induced GTP-binding protein Mx-1 (Mx-1) are a class of antiviral factors induced by IFN which play a crucial role in host resistance to viral infections." (PMID 41002440, 2025). "In MLE-12 cells, virus infection alone induced marked increases in Mx1 protein expression at 24 h, peaking at 36 hpi compared with controls (P < 0.01)." (PMID 40406095, 2025). "The results showed that, after RNF149 knockdown, cells produced higher levels of Cxcl10 and Mx1 following viral infection." (PMID 40245000, 2025). "DDX58 (RIG-I) plays a crucial role in the innate immune response against viral infections, while MX1 is involved in cellular antiviral responses." (PMID 39639868, 2024). "These GO terms collectively underscore MX1's role in not only halting the progression of viral infection but also in modulating the immune response to enhance efficacy and specificity." (PMID 39282474, 2024). "Expressions of MX1 appeared in the targets of the IFN-g pathway in response to viral infection with SARS-CoV-1 and SARS-CoV-2." (PMID 38666857, 2024). "Deficiencies in MX1 and ISG15 and in genes of the OAS group have been associated with higher susceptibility to viral infections in mice." (PMID 38236818, 2024). "The interferon (IFN)-stimulated gene (ISG) MX1 was induced upon treatment with IFN or viral infection, demonstrating functionality of key pathways of the IFN system." (PMID 38743751, 2024). "The broad inhibitory activity of MX1 is observed at an early post-entry step of the virus infection cycle, before the genome replication." (PMID 38877168, 2024). "MX1 plays a role in the salmon immune response to viral infections, notably myxoviruses such as ISAV, and spring viraemia of carp virus (SVCV)." (PMID 39211041, 2024).
viral infection (continued). "These cell lines expressed the podocyte marker podoplanin and expressed the IFN-stimulated gene (ISG) MX1 upon stimulation with IFN or viral infection." (PMID 37146034, 2023). "The results showed that the mRNA expression of IFN-β, IRF7, MDA5, TLR3, PKR, and MX-1 was significantly decreased in the overexpression group after viral infection, compared with the control group." (PMID 36995259, 2023). "RT-qPCR substantiated this observation, demonstrating that overexpression of circMerTK reduced the levels of IFN-β, ISG15, and MX1 mRNA following viral infection compared to the empty vector control." (PMID 36847523, 2023). "2′-5′-oligoadenylate synthetase-like (OASL) and myxovirus resistance 1 (MX1) are two of the most induced proteins in cells following IFN-I or viral infection." (PMID 36537793, 2023). "While it is well appreciated that interferons are important for control of viral infection in humans (19, –, 21), standard inbred mice lack a functional copy of Mx1 which mediates a large degree of this control against influenza viruses." (PMID 37695101, 2023). "Quantitative real-time PCR (qRT-PCR) was employed to demonstrate induction of MX1 expression upon stimulation with interferon (IFN) or viral infection, suggesting a functional IFN system." (PMID 37146034, 2023). "HERC6, IFI6, ISG15, and MX1 encode for proteins induced by type I interferons, such as IFN-α, IFN-β, IFN-ω, and are typically produced by host cells in response to viral infection." (PMID 35197051, 2022). "These transcriptional signatures of acute viral infection resolved in most cell types by day 7 after infection, with the exception of lingering MX1/MX2 expression in some populations of macrophages and DCs." (PMID 35653196, 2022). "For example, MX1 is a GTPase that inhibits viral infection by blocking viral transcription, replication, and assembly." (PMID 35972291, 2022). "Especially, many ISGs were modified with ubiquitin during viral infections such as MX1, MX2, OAS2, ISG15, and ISG20, which has rarely been reported before." (PMID 36071039, 2022). "IL-27 has been shown to play an important role in stimulating the transcription of cytosolic innate immune sensors, such as Mx1, Oas1, and Oas2, during viral infection." (PMID 36678402, 2022). "Similar to PARP9, as an important host interferon-stimulated gene in antiviral infection, MX1 (cg25888371) is hypomethylated in CpG after viral infection and then participates in regulating the defense response of the host to infection." (PMID 36212830, 2022). "Type I Interferon (IFN-I) is an important mediator of the innate immune response to viral infections, and Mx1 (mice and pigs, MxA in humans) is an integral downstream effector protein of the IFN-I antiviral response." (PMID 33648602, 2021). "When cells were instead treated with exogenous IFN after virus infection, MX1 promoter activity was reduced by rWT VHSV IVb infection compared to IFN treatment alone at 36 or 48 h post infection." (PMID 32365817, 2020). "We noticed that MX1 appeared multiple times across the studies, consistent with its great difference between bacterial and viral infections." (PMID 30524393, 2018). "To confirm these results we also studied by qPCR mRNA production of IFNβ and IFNβ-dependent genes such as Isg15, CXCL10 (an established marker of viral infection) or MX1." (PMID 29958295, 2018). "Other members of the network also reappeared in the gene set enrichment analysis as members of pathways associated with viral infections (DDX58, IFIT1, IRF1, MX1, STAT1) or viral carcinogenesis and cell cycle (CCND1, CCND3, CCNE1, CDC20, E2F2, RANBP1)." (PMID 30042828, 2018). "In this study, the expression of Mx1 gene, important for resistance against viral infection, and STAT1 were significantly induced." (PMID 28349053, 2017). "Viral infection induced a number of genes and proteins in the signaling pathway upon viral infections, we found that Mx1 and STAT1 mRNA levels can be induced in acute HIV-1 infection." (PMID 28623917, 2017).
viral infection (continued). "Cells displayed a marked upregulation of many genes known to be involved in the mammalian response to viral infection, including viperin, Mx1, IRF7, IRF1, and RIG-I with approximately 10% of the genes being uncharacterized transcripts." (PMID 29213275, 2017). "The knockdown of cGAS or STING completely abrogated IFNβ release and Ifnβ1 and Mx1 gene expression induced by viral infection or 8GyX3 treatment of TSA cells in vitro." (PMID 28598415, 2017). "A functional analysis of the bovine Mx1 protein revealed the gene’s antiviral action against various viral infections including VSV." (PMID 28066698, 2016). "The Mx1, Isg15, and Ddx58 mRNA expressions levels were significantly increased after virus infection." (PMID 27826541, 2016). "Exogenous G6PD or IDH1 expression inhibited the expression of HSCARG, resulting in increased expression of TNF-α and MX1 and reduced viral gene expression upon virus infection." (PMID 26694452, 2015). "Analysis of host genes germane to viral infections disclosed that antiviral genes such as mx1 and oas1 were induced in the HIV brains while MHC Class I genes (hla-c, -b and -a) were relatively suppressed in the same group." (PMID 23355888, 2013). "The interferon (IFN) response is an essential host defense program that limits viral infection and was shown here with the upregulation of many interferon-inducible genes including MX1, OAS1." (PMID 23881275, 2013). "The group includes genes of the innate response to viral infection that are interferon induced (ISGs): examples of this group include the six 2′-5′-oligoadenylate synthetase (Oas) genes, the Mx1 and Mx2 genes, Irf7 and Pkr." (PMID 18927629, 2008). "Additionally, innate immunity genes, like STAT1, ISG15, and MX1, were also found to be upregulated during viral infections, both in patients and in in vitro cultures." (PMID 41050093, 2025). "In addition to its direct antiviral properties, Mx1 expression and functionality are modulated by miRNAs, which play a significant role during viral infections." (PMID 40416980, 2025). "MX1, an antiviral cellular response factor, was also upregulated upon viral infection." (PMID 41157575, 2025). "Interestingly, our in vitro results revealed a discrepancy in Mx1 expression: although viral infection significantly elevated Mx1 mRNA levels, it unexpectedly reduced corresponding protein levels." (PMID 40406095, 2025). "The poly(I:C)-induced mx1 can enhance resistance to viral infections in salmonids." (PMID 39211041, 2024). "Likewise, in other species, the MX1 functions outside the immune response to viral infection during early pregnancy, perhaps in the processes of endometrial secretion or uterine remodeling accompanying pregnancy recognition." (PMID 38562608, 2024). "A greater number of genes are upregulated in DCs after MRV infection, many of which are involved in the innate immune response (i.e. Ifit1, Ifit3, Mx1, Gbp2, Oasl1, Isg15, Ccr1, Ifitm2, Oaxl2, Casp1, Casp4) that would be predicted in response to a viral infection." (PMID 38895117, 2024). "Under-expression of MX1, ISG15, RSAD2, IFIT1, and OAS2 may weaken the ability of the immune system to effectively counter viral infections, leaving the heart tissues susceptible to viral invasion and potentially contributing to MMVD progression." (PMID 38753730, 2024). "The increase in OAS2 and MX1 once again underscores a shared antiviral strategy across different viral infections, and ISG15 (interferon-stimulated gene 15) points to a broader modulation of the immune response, given its role in protein ubiquitination related to antiviral defense." (PMID 38655085, 2024). "Next, we characterized whether the cells expressed interferon β1 (IFNB1) or the interferon stimulated gene (ISG) MX1 in response to treatment with IFN or virus infection." (PMID 38743751, 2024).
viral infection (continued). "II) “Immune/virus infection regulation”, including MX1 and MX2." (PMID 38095646, 2023). "We next characterized whether the cells expressed interferon β (IFNB1) and the IFN-stimulated gene (ISG) MX1 in response to IFN or virus infection." (PMID 37146034, 2023). "The top 4 were “Cell matrix adhesion and organization” (COL6A1, COL6A2, COL18A1, JAM2, ADAMTS5 and POFUT2), “Immune/virus infection response” (MX1 and MX2), “Histone modification and chromatin remodeling” (NRIP1) and “Glycerolipid and lipid metabolism” (AGPAT3)." (PMID 38095646, 2023). "In addition, flow-cytometric detection of MX1 protein expression in whole blood appears to be an easy and valuable method for studying viral infections during acute asthma exacerbations." (PMID 36211429, 2022). "MX1 is induced by viral infection and exerts an antiviral action via its GTPase activity." (PMID 35391716, 2022). "We then tested whether gene transcription of Oas1-3 and Mx1 was dependent on Syk signaling since this previously has been demonstrated for viral infections." (PMID 36678402, 2022). "In addition to IAV, the antiviral function of murine Mx1 has been investigated in the context of a number of other viral infections." (PMID 35891527, 2022). "The Mx1 gene is induced by interferon α and β following viral infection." (PMID 36076303, 2022). "However, our results show that viral infection or genetic knockout of lincRNA‐EPS facilitates PKR‐STAT1 signaling axis induced antiviral genes such as Mx1, Oas2, Ifit2, and Irf7, while inhibits phosphorylation of TBK1 and IRF3, as well as the IFN‐β induction." (PMID 35312140, 2022). "We also show that IL22 reduces the expression of viral entry receptors (e.g. ACE2, TMPRSS2, DPP4, CD46 and TNFRSF14), increases the expression of anti-viral proteins (e.g. RSAD2, AOS, ISG20 and Mx1) and, consequently, reduces the viral infection of neighboring cells." (PMID 34045640, 2021). "We speculate that the up-regulation of MX1 expression in the liver may protect laying hens from viral diseases that are responsible for decreasing intensity of brown eggshell color." (PMID 33152221, 2021). "However, the effect of the VP4 protein on IFNβ, Mx1, or pro-inflammatory cytokines was reduced in the context of virus infection, compared to ectopic expression." (PMID 32582573, 2020). "A link between the gene expression of BIRC3 and MX1 has been hypothesized as part of a small group of genes controlling the host response against viral infections, including human herpes virus type 6Α (HHV-6Α) infection." (PMID 33301474, 2020). "Studies of the function of autoantibodies against type I interferon–related antiviral proteins, including MX1 and MDA5, in interstitial pneumonia might reveal a pathogenic relationship between viral infections, type I interferon signaling, and autoimmunity." (PMID 28230086, 2017). "Viral infection increased lung Mx1 and IP-10 expression in both strains of mice." (PMID 27701461, 2016). "Human myxovirus resistant protein A (MxA), encoded by the myxovirus resistance 1 (Mx1) gene, is an interferon (IFN)-triggered dynamin-like multi-domain GTPase involved in innate immune responses against viral infections." (PMID 26411585, 2015). "In addition, dozens ISGs, among which some have been characterized for their antiviral activities against various other viral infections, for example Mx1, Ifit1, Isg15, Ifi44, Ddx60, Oasl and Irf7 were up-regulated upon HDV inoculation in hNTCP-Tg mice." (PMID 25902143, 2015). "These IFNs are essential in the early control of virus infection as they facilitate the induction of over 300 IFN-stimulated genes including MX1, OAS1, and PKR that degrade viral RNAs and induce apoptosis, resulting in an antiviral state in the microenvironment." (PMID 26694447, 2015). "MX1 is responsible for a specific antiviral state against dozens of virus infection." (PMID 26465882, 2015). "The pig Mx1 protein is rapidly found in the cytoplasm in response to acute viral infections." (PMID 25408889, 2014).